BRCA1 (BRCA1 DNA repair associated)
Diseases named in the same sentence as BRCA1 in open-access papers (continued):
Sharing a sentence is not in itself a finding about the gene and the disease.
triple-negative breast carcinoma (continued). "Previous studies from our laboratory showed that PARP inhibitor effectively targeted triple negative breast cancer cells irrespective of their BRCA1 status." (PMID 28412751, 2017). "Protein expression of BRCA1 and LSD1 in triple negative breast cancer." (PMID 25679396, 2015). "There is a lack of studies investigating the burden of BRCA1/2 pathogenic variants (PVs) in Northern African countries using next-generation sequencing (NGS)-based testing in patients with epithelial ovarian (EOC) and triple-negative breast cancer (TNBC)." (PMID 40714512, 2025). "This study aimed to investigate the safety and efficacy of the combination of an mTOR/pan-PI3K inhibitor, gedatolisib, with the PARP inhibitor, talazoparib, in patients with advanced triple negative breast cancer or advanced HER2 negative breast cancer and a germline BRCA1/2 mutation." (PMID 40471518, 2025). "Additionally, cluster 2 was also significantly associated with gender (p = 0.015), HER2 positive (p < 0.001), and triple-negative breast cancer (p = 0.005), but not BRCA1, BRCA2, ER, and PR (p > 0.05)." (PMID 34650974, 2021). "BRCA1 loss of function mutations are associated with high-histological-grade, oestrogen-receptor-negative, progesterone-receptor-negative, and HER2-negative (triple negative) breast cancer with a basal-like gene expression profile." (PMID 29337092, 2018). "We selected the DLD-1 human colorectal carcinoma cell line for its normal karyotype and a high mutagenic rate due to microsatellite instability, and the SUM149PT BRCA1 mutant triple-negative breast carcinoma cell line for highest relevance to PARPI treatment and no detectable BRCA1 protein." (PMID 30425352, 2018). "However, BRCA1/2 carriers were more likely to be triple-negative breast cancer compared with non-carriers (62.5 vs. 16.7 %, p = 0.02)." (PMID 27129401, 2016). "However, we observed BRCA1 promoter methylation in the triple negative breast carcinoma of patient 1, but not in glioblastoma." (PMID 25880076, 2015). "However, in our study, we found that simultaneous treatment of low dose of DNA-PK-i and PARP-i induces synthetic lethality in a triple-negative breast cancer cell line lacking BRCA1, which is elicited through defects in pre-rRNA biogenesis, but not DNA damage response." (PMID 38682589, 2024). "According to the treatment guidelines for advanced triple negative breast cancer (TNBC), patients are only eligible for treatment with the poly(ADP-ribose) polymerase (PARP) inhibitor olaparib after undergoing first-line systemic non-targeted chemotherapy, and only if they carry a BRCA1/2 mutation." (PMID 32630796, 2020). "Therefore, we hypothesize that the other possible reason for the development of BRCA1 defective triple negative breast cancer could be the influence of β-hCG, which has not been analyzed till now." (PMID 28869585, 2017). "One could hypothesize from these findings that the BRCA1-3’UTR-variant functions similarly to that of canonical BRCA1 open-reading-frame variants, which are more commonly associated with development of triple negative breast cancer as opposed to the other subtypes." (PMID 24915755, 2014). "We generated new BRCA1 isogenic cell line pairs from both a triple-negative breast cancer cell line (SUM149) and adapted pre-existing non-cancerous BRCA1 isogenic pair (RPE)." (PMID 40982437, 2025). "Receptor expression profiling of BRCA1 mutant tumors showed that their vast majority proved to be ER-alpha negative and ER/PR/HER2 negative, nominated as triple negative breast cancer (TNBC)." (PMID 38672654, 2024). "The Treating to New Targets trial did not demonstrate a role for HRD testing to identify patients with wild-type BRCA1 and BRCA2 who have advanced triple-negative breast cancer more likely to benefit from carboplatin as opposed to taxane chemotherapy." (PMID 36253484, 2022).
triple-negative breast carcinoma (continued). "We aim to report a retrospective analysis of BRCA1/2 and non-BRCA gene sequencing in patients with breast/ovary cancer (BOC), including triple-negative breast cancer (TNBC), in our population." (PMID 34072659, 2021). "The aim of this report is to describe a retrospective analysis of BRCA1/2 and non-BRCA gene sequencing in patients with breast/ovary cancer (BOC), including triple-negative breast cancer (TNBC)." (PMID 34072659, 2021).
pancreatic cancer (424 papers, 2004 to 2026). "It has been demonstrated that the risk of pancreatic cancer is increased in patients with loss-of-function BRCA1 and BRCA2 mutations." (PMID 40124650, 2025). "Pathogenic BRCA1/2 mutations are strongly linked to breast, ovarian, prostate, gastric, colorectal, and pancreatic cancers." (PMID 41294693, 2025). "While BRCA1 defects are linked with a highly penetrant cancer syndrome (involving breast, ovarian, and pancreatic cancer), their association with skin cancers remains unestablished, as ECs were excluded from prior studies." (PMID 40948682, 2025). "Individuals carrying BRCA1/2 mutations face an increased risk of developing breast, ovarian, prostate, and pancreatic cancers." (PMID 40136510, 2025). "It has been shown that advanced pancreatic cancer with biallelic loss of BRCA1 and BRCA2 had a higher median tumor mutation burden than wild type tumors with the consequent possible higher sensitivity to ICIs." (PMID 40124650, 2025). "Therapeutic methods for pancreatic cancer patients with specific genetic mutations, such as BRCA1 or BRCA2 mutations and KRAS mutations, are currently being researched." (PMID 40948342, 2025). "Among 15 participants with pancreatic cancer (PC) and BRCA1/2 mutations, 4 achieved partial responses, which was remarkable given the inclusion of heavily pretreated and platinum-refractory cases." (PMID 40951294, 2025). "PARPi are effective only in a small subset of pancreatic cancers that harbor BRCA1/2 mutations, as the majority of cases remain resistant to PARPi due to proficient BRCA1 activity." (PMID 40764600, 2025). "As more clinical trials have demonstrated its efficacy and safety, olaparib has been approved for pancreatic cancer, breast, and ovarian with BRCA1/2 mutations." (PMID 37588193, 2024). "This is the first study to demonstrate synergistic interactions between PARPis (olaparib or talazoparib) and panobinostat, vorinostat, and decitabine in pancreatic cancer cell lines with wild-type BRCA1/2 (BxPC-3 or PL45) or BRCA2 mutation (Capan-1)." (PMID 38829622, 2024). "The risk of pancreatic cancer is 1–3% in patients with a BRCA1 mutation and 3–5% by the age of 70 years in patients with a BRCA2 mutation as compared to the general population with a risk of 0.5%." (PMID 39200847, 2024). "Most familial pancreatic cancer is attributable to hereditary breast and ovarian cancer syndrome that results from germline mutations in BRCA1/2 genes and other genes such as ATM, BRIP1, CHEK2, RAD50, and RAD51C." (PMID 38732320, 2024). "reviewed all published clinical cases reporting BRCA1/2 reversion mutations in cancers of the BRCA1/2 spectrum, namely ovarian, breast, prostate, and pancreatic cancers." (PMID 38544832, 2024). "The ongoing phase I/IIa PETRA trial (NCT04644068) has enrolled 61 patients with advanced HER2-negative breast, ovarian, prostate, or pancreatic cancer who had germline or somatic BRCA1/2, PALB2, or RAD51C/D loss-of-function mutations." (PMID 37588193, 2024). "BRCA1/2 mutations, present in approximately 10% of pancreatic cancer cases, have emerged as important biomarkers." (PMID 39575418, 2024). "Individuals of both genders bearing harmful BRCA1 or BRCA2 variants face augmented risks of pancreatic cancer, albeit the degree of risk elevation is comparatively modest." (PMID 38809921, 2024). "A PARP inhibitor, olaparib (Ola), is also indicated for treating patients with advanced pancreatic cancer with loss-of-function mutations in the germline BRCA1/2 gene and remaining sensitivity to the platinum-based anticancer drugs." (PMID 37956396, 2024). "Mutations in BRCA1/2 genes (BRCAm) were most frequently identified in ovarian (OvCa, 15.2%) followed by prostate (PC, 10.7%), breast (BC, 8.8%) and pancreatic cancer (PaC, 5.2%)." (PMID 38184614, 2024).
pancreatic cancer (continued). "Rucaparib maintenance is a safe and effective therapy for platinum-sensitive advanced pancreatic cancer with BRCA1/2 or PALB2 pathogenic variant." (PMID 37588193, 2024). "A recent study on the molecular mechanism of BRCA mutations and CAF in pancreatic cancer reported enhancement of clusterin in BRCA1 or BRCA2 mutant CAF in a heat shock factor 1-dependent manner." (PMID 38182557, 2024). "Known gBRCA carrier individuals have a higher lifetime risk of developing pancreatic cancer compared to the normal population (with BRCA1: 2.2–3.0%; with BRCA2: 3.0–7.0%)." (PMID 38540206, 2024). "In cancers such as breast and pancreatic cancers, Signature 3 is strongly associated with germline or somatic BRCA1/BRCA2 mutations, which are well-established indicators for susceptibility to PARP inhibitors." (PMID 38939336, 2024). "This article will review the latest evidence-based management of breast, ovarian, prostate and pancreatic cancer associated with BRCA1/2 PVs/LPVs as well as discuss some of the challenges in oncology therapeutics." (PMID 39796639, 2024). "Rucaparib was proven to be a safe and effective therapy for platinum-sensitive, advanced pancreatic cancer with a pathogenic variant in BRCA1, BRCA2, or PALB2." (PMID 38540206, 2024). "Signature 3 has been previously reported in breast and pancreatic cancers and shows a strong association with germline and somatic BRCA1 and BRCA2 mutations, leading to defective homologous recombination repair of DNA double-strand breaks." (PMID 38315150, 2024). "Germline BRCA1/2 mutations were found in 6.7–9.7% of pancreatic cancers, indicating that pancreatic cancer is a phenotype of HBOC syndrome." (PMID 37956396, 2024). "According to a different study, mutations in BRCA1/2 were most commonly detected in ovarian (15.2%), prostate, (10.7%) breast (8.8%) and pancreatic cancer (5.2%)." (PMID 38184614, 2024). "The detection of BRCA1/2 mutations offers numerous benefits, particularly in its correlation with familial pancreatic cancer (FPC)." (PMID 38809921, 2024). "Poly (ADP-ribose) polymerase inhibitor is another promising drug for pancreatic cancer patients harbouring BRCA1/2 pathogenic germline variants." (PMID 37951914, 2023). "The synergistic effect of the PARP inhibitor and of platinum-based chemotherapy was assessed in a randomized phase 2 study including treatment-naive patients with pancreatic cancer with germline BRCA1/2 or PALB2 mutations." (PMID 37366887, 2023). "PARP inhibitors are drugs that inhibit PARP enzymes and constitute the only targeted therapies used in pancreatic cancer indicated for tumors with germline BRCA1/BRCA2 mutations." (PMID 36975505, 2023). "For example, pancreatic cancer patients appear to benefit especially from platinum-based chemotherapy when a BRCA-1/2 germline mutation is present." (PMID 36765639, 2023). "Pancreatic cancers associated with BRCA1/2 mutations have emerged as a distinct subgroup with sensitivity to other treatments and, in some cases, durable responses." (PMID 37296917, 2023). "In contrast, the sensitivity of pancreatic cancers with somatic BRCA1 and BRCA2 mutations and with mutations in other homologous recombination (HR) repair genes to PARP inhibitors is less established and the subject of ongoing investigations." (PMID 36975505, 2023). "Compared with the ample data on PARP inhibitors in pancreatic cancers with germline BRCA1/BRCA2 mutations, data on cases with somatic mutations in the two genes are sparse." (PMID 36975505, 2023). "PARP inhibitors in germline BRCA1/2-mutated pancreatic cancer has been one targeted therapy success." (PMID 36670111, 2023). "The present study aimed to investigate the prevalence of BRCA1/2 pathogenic germline variants among pancreatic cancer patients from Pakistan." (PMID 37951914, 2023).
pancreatic cancer (continued). "In contrast, a benefit from PARP inhibitors in pancreatic cancer in other settings, such as somatic BRCA1/BRCA2 mutations, and in pancreatic cancers with mutations in non-BRCA1/BRCA2 DNA damage response (DDR)-associated genes is less clear." (PMID 36975505, 2023). "Enhanced sensitivity of BRCA1/2-mutated cancers to platinum salts has been well documented in numerous studies, for instance, those on OC, pancreatic cancer, and BC." (PMID 36902416, 2023). "For example, BRCA1, found in one patient with eoCRC, confers an increased risk of breast, ovarian, prostate, and pancreatic cancer." (PMID 37509234, 2023). "A recent study found that 7% of Canadian patients diagnosed with pancreatic cancer carry mutations in the BRCA1 and BRCA2 genes, with a higher prevalence observed in patients diagnosed at younger ages." (PMID 37232812, 2023). "Germline variants in BRCA1/2 were represented at high frequencies among breast, ovarian, prostate and pancreatic tumors, although germline BRCA1/2 variants were also found in primary lung, sarcoma, and other tumor types (at a lower proportion of the total)." (PMID 36261688, 2023). "The remaining 150 unselected pancreatic cancer patients were comprehensively screened for BRCA1/2 variants using DHPLC and HRM analyses followed by DNA sequencing." (PMID 37951914, 2023). "PARP inhibitors, including olaparib, niraparib, veliparib, rucaparib, and talazoparib, have achieved promising therapeutic outcomes and conferred clinically meaningful benefits to pancreatic cancer patients with BRCA1/2 mutations." (PMID 37415733, 2023). "This is the first comprehensive study investigating the contribution of BRCA1/2 germline variants to unselected pancreatic cancer patients from Pakistan." (PMID 37951914, 2023). "The frequency of BRCA1/2 pathogenic variants in pancreatic cancer patients varies widely across ethnic groups and geographic regions." (PMID 37951914, 2023). "Recently, PARP inhibitors have been approved for the treatment of pancreatic cancer patients with BRCA1/2 mutations, which opens a new era of precision medicine for pancreatic cancer." (PMID 37415733, 2023). "Most of the clinical trials that involve molecular profiles of the pancreas tumour are those including patients with germline BRCA1/BRCA2 pathogenic variants." (PMID 36765737, 2023). "We aimed to investigate the prevalence of BRCA1/2 germline variants in Pakistani pancreatic cancer patients." (PMID 37951914, 2023). "This is the first comprehensive study investigating the contribution of BRCA1/2 variants to a cohort of 150 unselected and prospectively registered pancreatic cancer patients from Pakistan." (PMID 37951914, 2023). "In this first study, BRCA1/2 pathogenic variant is identified with a low frequency in pancreatic cancer patients from Pakistan." (PMID 37951914, 2023). "A benefit of maintenance olaparib versus placebo in prolonging PFS in first-line metastatic pancreatic cancer patients with germline BRCA1/BRCA2 mutations was observed in the Pancreas Cancer Olaparib Ongoing (POLO) phase III randomized double-blind trial." (PMID 36975505, 2023). "A cohort of 29 advanced pancreatic cancer patients with deleterious germline mutations in BRCA1/BRCA2 or PALB2 had longer OS (median OS 21.8 months versus 8.1 months) than matched controls without mutations." (PMID 36975505, 2023). "The lifetime risk conveyed by BRCA1 in pancreatic cancer is significantly lower (estimated to be 3 per cent) and falls below the general cut-off risk to initiate screening." (PMID 37165697, 2023). "In patients with hereditary pancreatic cancer, the prevalence of BRCA1/2 mutation carriers is estimated at 4.9–26%." (PMID 36902416, 2023). "Whereas BRCA1/2 pathogenic variants have been reported in familial pancreatic cancer patients with a prevalence of 0.8% (5/638) to 7.3% (9/124) in large studies (> 100 patients) from the USA and Canada." (PMID 37951914, 2023).